ADORA2A (adenosine A2a receptor)
Diseases named in the same sentence as ADORA2A in open-access papers (continued):
Sharing a sentence is not in itself a finding about the gene and the disease.
heart failure (4 papers, 2012 to 2021). Inability of the heart to pump blood at an adequate rate to meet tissue metabolic requirements. "Our in vivo experiments clearly underline that reduced expression of LY75 and ADORA2A in cardiomyocytes leads to heart failure as observed in our patients." (PMID 23341106, 2013). "Since LY75 and ADORA2A were not previously known to be involved in DCM or heart failure pathogenesis and both showed significant downregulation in the myocardium of DCM patients, we investigated their functional roles by gene knockdown in zebrafish embryos." (PMID 23341106, 2013). "We detected methylation differences in pathways related to heart disease, but also in genes with yet unknown function in DCM or heart failure, namely Lymphocyte antigen 75 (LY75), Tyrosine kinase-type cell surface receptor HER3 (ERBB3), Homeobox B13 (HOXB13) and Adenosine receptor A2A (ADORA2A)." (PMID 23341106, 2013).
mood disorder (4 papers, 2014 to 2025). A cognitive disorder a disturbance in which the person's mood is hypothesized to be the main underlying feature. "Polymorphisms in ADORA2A may modulate psychomotor vigilance and sleep EEG and it has been previously noted that DRD2 variants are associated with mood disorders." (PMID 25340473, 2014).
osteoarthritis (4 papers, 2020 to 2025). A noninflammatory degenerative joint disease occurring chiefly in older persons, characterized by degeneration of the articular cartilage, hypertrophy of bone at the margins and changes in the synovial membrane. "This agonist induced ADORA2A effect was also observed in human chondrocytes, so that ADORA2A signaling seems to be ligated to mitochondrial and oxidative protection in osteoarthritis." (PMID 35079944, 2022). "The absence of ADORA2A in primary murine chondrocytes promoted spontaneous osteoarthritis with concomitant mitochondrial damage (swelling, reduced mitochondrial content and dysfunction) and ROS-induced oxidative damage." (PMID 35079944, 2022).
ovarian carcinoma (4 papers, 2016 to 2025). A malignant neoplasm originating from the surface ovarian epithelium. "This might further explain the very potent effects observed with anti-CD73 and anti-ADORA2A directed strategies in animal tumor models – and it could show a new strategy to interfere with MDSC, TAM and their tumor-promoting role in ovarian cancer." (PMID 27532024, 2016).
scleroderma (4 papers, 2008 to 2023). Scleroderma is a rare autoimmune connective tissue disorder characterized by abnormal hardening of the skin and, sometimes, other organs. "The adenosine A2A receptor is overexpressed in fibroblasts of scleroderma patients presenting excessive collagen deposition in the skin and the visceral organs." (PMID 32156055, 2020). "In summary, the results of our present work confirm previous observations of the role of the adenosine A2A receptor in the pathogenesis of dermal fibrosis in conditions such as scleroderma by promoting the production of tissue matrix and profibrotic mediators." (PMID 23663495, 2013). "Our results suggest that Fli1 and CTGF are important mediators of the fibrogenic actions of adenosine and the use of small molecules such as adenosine A2A receptor antagonists may be useful in the therapy of dermal fibrosis in diseases such as scleroderma." (PMID 23663495, 2013).
type 2 diabetes (4 papers, 2012 to 2023). "In a recent study on PDR of patients with type 2 diabetes, microarray analysis of gene expression in fibrovascular membranes showed that the level of ADORA2A mRNA was much higher in samples excised from patients with PDR compared with those from patients with non-PDR51." (PMID 28928465, 2017).
viral diseases (4 papers, 2019 to 2024). "Adora2a and Kdr have both been implicated as negative regulators of CD8+ T cells in the TME33,34, but have not been studied in the context of LCMV viral infection." (PMID 30971695, 2019).
dilated cardiomyopathy (3 papers, 2020 to 2024). Cardiomyopathy which is characterized by dilation and contractile dysfunction of the left and right ventricles. "Additionally, in patients with dilated cardiomyopathies, association of aberrant DNA methylation was observed with significant differences in expression of ADORA2A and LY75 mRNA." (PMID 38314203, 2024). "In Zebra fish model, it was observed that methylation of ADORA2A (adenosine A2a receptor) and LY75 (lymphocyte antigens) were associated with human dilated cardiomyopathy." (PMID 36551003, 2022). "Additionally, epigenomic studies of dilated cardiomyopathy patients found that abnormal DNA methylation changed mRNA expression of LY75 and ADORA2A with later studies linking 517 loci with dilated cardiomyopathy." (PMID 33202590, 2020).
enteritis (3 papers, 2012 to 2021). Inflammation of the small intestine. "This study investigates the protection from enteritis by combination therapy with ATL 370, an adenosine A2A receptor agonist, and alanyl-glutamine in a rabbit and murine intestinal loop models of C. difficile toxin A-induced epithelial injury." (PMID 22264229, 2012). "This study has shown that adenosine A2A receptor agonist, ATL 370, ameliorates C. difficile toxin A-induced intestinal epithelial disruption, inflammation and secretion in the ligated loop model of enteritis in rabbits." (PMID 22264229, 2012).
Gilles de la Tourette Syndrome (3 papers, 2015 to 2024). "Genotypic and allelic association analysis of ADORA1 rs2228079 and ADORA2A rs5751876 variants with co-morbid disorders in patients with Gilles de la Tourette syndrome." (PMID 26317759, 2015). "Recently, studies have shown the association of adenosine and its receptor (ADORA1, Adenosine A2A Receptor [ADORA2A]) with many CNS disorders such as attention deficit hyperactivity disorder (ADHD) and Gilles de la Tourette syndrome." (PMID 35628334, 2022).
malaria (3 papers, 2010 to 2023). Malaria is a serious and sometimes fatal disease caused by a parasite that commonly infects a certain type of mosquito which feeds on humans. "Accumulating evidence, including the ADORA2A association reported in this study, indicates that the Gs signal transduction pathway is involved in the regulation of malaria, and more specifically, in the severe, life threatening manifestations of this disease." (PMID 20386734, 2010). "In this study, and, to the best of our knowledge, the first candidate-based investigation of ADORA2A in severe malaria, we demonstrate significant association with this gene using meta-analysis across case-control and TDT studies from The Gambia and Malawi." (PMID 20386734, 2010). "The mechanism by which the ADORA2A associations presented here might elicit a pathogenic effect in malaria disease remain unclear." (PMID 20386734, 2010). "Thus, in addition to a potential role in regulating erythrocyte invasion, ADORA2A may mediate susceptibility to severe malaria via regulation of inflammatory cytokine levels." (PMID 20386734, 2010). "The significant changes observed in the expression of ectonucleotidases and the adenosine receptors ADORA2a and ADORA2b in monocyte subsets, suggest a role for adenosine in malaria." (PMID 37545509, 2023). "This should enhance our understanding of how ADORA2A is involved in the regulation of severe malaria pathology." (PMID 20386734, 2010).
pancreatic cancer (3 papers, 2023 to 2024). "While no functional experiments were reported in this manuscript, these data indicate both autocrine and paracrine adenosine signaling through Adora2a are important in the pathogenesis of pancreatic cancer." (PMID 37187740, 2023). "CD73 transcriptionally upregulates CCL5 through tumor cell-autocrine adenosine–Adora2a signaling-mediated activation of the p38–STAT1 axis, recruiting Tregs to pancreatic tumors and causing an immunosuppressive microenvironment." (PMID 37291128, 2023). "In the current study, we found that CD73 activates the p38–STAT1 axis through tumor cell-autocrine adenosine–Adora2a signaling, which results in the upregulation of CCL5 and further Treg recruitment in pancreatic cancer." (PMID 37291128, 2023). "Specifically, in pancreatic cancer patients, studies show CD73 and Adora2a expression on neoplastic or tumor cells correlates with divergent immune cell populations in the tumor microenvironment." (PMID 37187740, 2023). "In this study, we find a synergistic inhibitory effect of co-targeting CD73 and immune checkpoints in pancreatic cancer and demonstrate the significant role of tumor cell-autonomous CD73 and tumor cell-autocrine adenosine–Adora2a signaling in stimulating CCL5 transcription and Treg recruitment." (PMID 37291128, 2023). "Of the four receptors, Adora2a and Adora2b have been reported as high in PDAC and are overexpressed in the pancreas during pancreatic cancer; yet only high expression of Adora2b receptor was shown to correlate with significantly reduced survival in PDAC patients." (PMID 37187740, 2023).
psychostimulant addiction (3 papers, 2009 to 2021). "Our findings, together with previous studies, make it plausible that caffeine through adenosine A2A receptor-mediated phosphorylation of TH at Ser31, results in the dopaminergic neuroadaptations related to the treatment of PD and mechanism of drug dependence/addiction." (PMID 20074377, 2010).
sickle cell disease (3 papers, 2017 to 2023). Sickle cell anemias are chronic hemolytic diseases that may induce three types of acute accidents: severe anemia, severe bacterial infections, and ischemic vasoocclusive accidents (VOA) caused by sickle-shaped red blood cells obstructing small blood vessels and capillaries. "Selective adenosine A2A receptor (A2AR) agonists such as regadenoson (RA) reduce inflammation in most tissues, including lungs injured by hypoxia, ischemia, transplantation, or sickle cell anemia, principally by suppressing the activation of invariant natural killer T (iNKT) cells." (PMID 37566593, 2023).
cerebral small vessel disease (2 papers, 2022 to 2023). Cerebral small vessel disease is the term currently used to pathological processes that affect the brain parenchymal circulation (arterioles, capillaries, and veins). "Our study provides a new potential target, ADORA2A, for the treatment of cerebral small vessel disease in clinical practice." (PMID 35237278, 2022). "Additionally, the mechanism through which ADORA2A alleviates CCH-induced white matter injury was investigated to identify possible targets that could be used for the clinical treatment of cerebral small vessel disease and thereby improve the quality of life of affected patients." (PMID 35237278, 2022). "Another study showed that the activation of adenosine A2A receptor could inhibit the expression of YKL-40 and thereby alleviate white matter injury in cerebral small vessel disease." (PMID 36880855, 2023).
chronic periodontitis (2 papers, 2022 to 2025). A chronic inflammatory process that affects the tissues that surround and support the teeth. "Here, we investigated the effects of selective adenosine A2a receptor (A2aR) stimulation using the agonist CGS21680 in a mouse model of ligature-induced periodontitis (LIP) and in gingival fibroblast mitochondrial function." (PMID 40862745, 2025). "In the present study, our main finding was that adenosine A2a receptor stimulation mitigated periodontitis." (PMID 40862745, 2025). "This study examined whether the protective effects of adenosine in gingival inflammation and periodontitis were due to adenosine A2a receptor (A2aR) stimulation." (PMID 40862745, 2025).
diabetic foot ulcers (2 papers, 2004 to 2006). "Recent studies have demonstrated that application of topical adenosine A2A receptor agonists promotes more rapid wound closure and clinical studies are currently underway to determine the utility of topical A2A adenosine receptor agonists in the therapy of diabetic foot ulcers." (PMID 14755098, 2004).
ischemic colitis (2 papers, 2020 to 2021). Inflammation of the colon due to colonic ischemia resulting from alterations in systemic circulation or local vasculature. "Induction of ischemic colitis increased TNF-α, IL-1β, and IL-6 expressions, whereas decreased adenosine A2A receptor expression (P < 0.05)." (PMID 32149087, 2020). "Likewise, PDRN + DMPX treatment showed no change in adenosine A2A receptor expression compared to ischemic colitis group." (PMID 32149087, 2020).
liver cancer (2 papers, 2024 to 2025). An epithelial or non-epithelial malignant neoplasm that arises from the liver. "While not yet in clinical trials, adenosine A2a receptor (A2aR) inhibition has been combined with anti-PD-1 therapy, leading to the activation of T cells and reductions in tumor size in orthotopic murine liver cancer models." (PMID 39858016, 2025).
mental disorder (2 papers, 2018). A disease that has its basis in the disruption of mental process. "Specially, the crucial neuroactive ligand-receptor interaction pathway has been applied into the analysis of mental disorders, which is regulated by 25 potential targets (ADORA1, ADORA2A, ADORA3, etc.)." (PMID 30127739, 2018).
retinal degeneration (2 papers, 2020 to 2022). Degeneration of the retina. "This work aimed to evaluate the potential neuroprotective effect of the modulation of adenosine A2A receptor in the model of light-induced retinal degeneration." (PMID 35387355, 2022).
retinal detachment (2 papers, 2020 to 2022). An eye emergency condition which may lead to blindness if left untreated. "Adenosine A2A receptor (A2AR) signaling is neuroprotective in some retinal damage models, but its role in neuronal survival during retinal detachment (RD) is unclear." (PMID 32714489, 2020).
Right ventricular hypertrophy (2 papers, 2017 to 2022). In this case the right ventricle is more muscular than normal, causing a characteristic boot-shaped (coeur-en-sabot) appearance as seen on anterior- posterior chest x-rays. "Treatment with 32 mg/kg salidroside significantly reversed the hypoxia-induced right ventricular hypertrophy primarily through upregulating the adenosine A2a receptor (A2aR)-related mitochondria-dependent apoptosis pathway." (PMID 35033157, 2022).
acute pancreatitis (1 paper, 2022). An acute inflammatory process that leads to necrosis of the pancreatic parenchyma. "Activation of the adenosine A2A receptor decreased the inflammatory cell infiltration and acinar cell necrosis in acute pancreatitis and the mRNA level of A2A was much higher than that of other receptors in the pancreas." (PMID 35281076, 2022).
adenoma (1 paper, 2013). A neoplasm arising from the epithelium. "However, for ADORA2A, varying levels of expression were observed between adenomas." (PMID 23788688, 2013).
brain tumors (1 paper, 2021). "Despite the scant amount of in vivo and clinical trials, the authors made an effort to evaluate the clinical usefulness of adenosine A2A receptor agonists in a cotreatment of brain tumors." (PMID 33923147, 2021).
Burkitt lymphoma (1 paper, 2023). A rare form of malignant mature B-cell non-Hodgkin lymphoma. "Notably, the expression of Adora2a was considerably lower in PEL cells than in other cell lines examined, while the expression of Adora2b was elevated in most Burkitt lymphoma cell lines." (PMID 36786572, 2023).
childhood encephalopathy (1 paper, 2018). "Also, genetic polymorphisms of A2AR (ADORA2A) are associated with childhood encephalopathy resulting from biphasic seizures." (PMID 30627646, 2018).
chronic heart failure (1 paper, 2020). "In addition to the functional relevance of the ADORAs in blood lipid profiles and lipid-related chronic diseases, a genetic variant of ADORA2A showed association with the severity of chronic heart failure in Asians." (PMID 32075205, 2020).
coagulopathies (1 paper, 2021). "Further data analysis and interpretation suggested the involvement of acute activation of TGFβ1, IL1β, and ADORA2A signaling, as well as the increased levels of fibrinogens and fibronectin to block coagulopathies." (PMID 33668155, 2021).
diabetic eye disease (1 paper, 2017). A group of disorders affecting the eye in patients with diabetes mellitus. "Indeed, we found that ADORA2A knockdown led to a marked reduction in VEGF-induced HRMEC sprouting and tube formation, suggesting a facilitating role of ADORA2A in the VEGF pathway, the molecular target of current treatments for diabetic eye diseases." (PMID 28928465, 2017).
Encephalopathy (1 paper, 2020). Encephalopathy is a term that means brain disease, damage, or malfunction. "The genetic polymorphism of ADORA2A was found to be associated with encephalopathy with febrile status epilepticus, ADHD traits, and abnormal neurobehavioral performance during sleep restriction." (PMID 33262686, 2020).
fracture (1 paper, 2020). "The aim of this study was to explore the effect of adenosine A2A receptor agonists on fracture healing and the regulation of the immunity system after bone fracture." (PMID 32382539, 2020).
Headache (1 paper, 2017). Cephalgia, or pain sensed in various parts of the head, not confined to the area of distribution of any nerve. "Adenosine A2A receptor signaling may contribute to headache via the modulation of intracellular Cyclic adenosine monophosphate (cAMP) production or 5' AMP-activated protein kinase (AMPK) activity in neurons and glia to affect glutamatergic synaptic transmission within the brainstem." (PMID 28335379, 2017).
heart neoplasm (1 paper, 2014). A neoplasm (disease) that involves the heart. "In agreement with several lines of evidence involving the purinergic adenosine A2a receptor in immune evasion of tumor cells, we find that regadenoson, an A2a receptor agonist, shares phenotypic features with heart neoplasms." (PMID 25276232, 2014).
hepatoblastoma (1 paper, 2024). Hepatoblastoma (HB) is a malignant hepatic tumor and is the most common pediatric liver cancer. "In detail, we performed cell-line drug response and viability assays on the human HEPG2 hepatoblastoma cell line for CGS-15943, an ADORA2A and ADORA1 inhibitor, which is reported to act against multiple adenosine receptors, and MRS-1220, an ADORA3 and ADORA2B inhibitor." (PMID 38723607, 2024).
idiopathic dilated cardiomyopathy (1 paper, 2019). Decreased function of the heart associated with cardiac enlargement and congestive heart failure, of unknown cause. "Genome-wide cardiac DNA methylation in idiopathic dilated cardiomyopathy patients revealed abnormal DNA methylation, which was related to important variations in the expression of lymphocyte antigen 75 (LY75) and adenosine receptor A2A (ADORA2A) mRNA." (PMID 31649728, 2019).
keloid (1 paper, 2024). An irregularly shaped, elevated mark on the skin caused by deposits of excessive amounts of collagen during wound healing. "This work prepared and investigated the impact of carboxymethyl chitosan nanoparticles (MC-NPs) on the proliferative capability of keloid fibroblasts (KFBs) while analyzing the mechanistic roles of miR-214 and adenosine A2A receptor (A2AR) in fibroblasts within hypertrophic scars." (PMID 38418830, 2024).
Leukoencephalopathy (1 paper, 2025). This term describes abnormality of the white matter of the cerebrum resulting from damage to the myelin sheaths of nerve cells. "One study demonstrated that polymorphisms in the ADORA1 adenosine A2A receptor and ADORA2A gene were associated with methotrexate-related leukoencephalopathy in children with ALL." (PMID 41009999, 2025).
lymphoproliferative disorder (1 paper, 2017). "Using a genetic approach, we found that adenosine A2A receptor deletion in SF mice (SF⋅A2A-/-) does not affect early life events, the development of a lymphoproliferative disorder, or hyper-production of pro-inflammatory cytokines seen in the Treg-deficiency state." (PMID 29270168, 2017).